TH (tyrosine hydroxylase)
Diseases named in the same sentence as TH in open-access papers (continued):
Sharing a sentence is not in itself a finding about the gene and the disease.
diabetes (continued). "In addition, GA attenuated diabetes-induced upregulation of cleaved caspase-3 and glutamate and counteracted the downregulation of synaptophysin, TH, GS, and GLO1 induced by diabetes without changing body weight or blood glucose levels." (PMID 24733965, 2014). "While there are similarities among innervation patterns with NF200, TH, and VAChT, our studies do not allow us to determine whether the changes in pancreatic innervation with diabetes are generalized or specific to sympathetic, parasympathetic, or sensory pathways." (PMID 33036983, 2020). "We found no significant changes in levels of mRNAs encoding TH, the transcription factors nuclear receptor‐related 1 protein (Nurr1) and LIM homeobox transcription factor 1 beta (Lmxb1), or the dopamine D2 autoreceptors, indicating that diabetes per se did not affect the integrity of these neurons." (PMID 32666590, 2020). "Furthermore, diabetes alters the expression of several genes involved in mitochondrial stress (including mitochondrial membrane pore protein VDAC1, aconitase 2 and heme oxygenase-1) and neuronal injury (such as tyrosine hydroxylase and synaptic protein synaptopodin)." (PMID 28492550, 2017).
Hypertension (22 papers, 2010 to 2025). The presence of chronic increased pressure in the systemic arterial system. "Immunofluorescence staining shows that hypertension in SHRs is associated with increased production of TH in the PVN which was reduced by the chronic infusion of luteolin in SHRs but not in WKY rats." (PMID 36771206, 2023). "Besides that, upregulated hypothalamic and renal tyrosine hydroxylase have been identified in obese and/or hypertensive rats and the development of hypertension in cafeteria-fed rats is associated with changes in the renal subtypes of adrenergic α2 receptors." (PMID 34065436, 2021). "The impairment in proteasome activity observed in SHR neurons may be one of the causes of the increased TH protein levels reported in hypertension." (PMID 25710381, 2015). "Hypertension may be associated with alterations in tyrosine hydroxylase activity." (PMID 31572179, 2019). "In a high-salt diet-induced hypertension rat model, TH and norepinephrine expression increase in the PVN of the hypothalamus, and antioxidant infusion can reverse these changes." (PMID 39234603, 2024). "Previous studies of our group showed that NF-κB activation and TH expression increased in the PVN of hypertension or heart failure rat models, whereas inhibition of NF-κB decreased TH expression in the PVN of heart failure rats." (PMID 36235829, 2022). "Our laboratory studies and those of others have shown increased TH expression and decreased GAD67 expression in the PVN during hypertension and heart failure, causing an imbalance between excitatory and inhibitory neurotransmitters." (PMID 36235829, 2022). "Activation of AT2 receptors or Mas receptors prevents the onset of myocardial fibrosis and hypertrophy in Ang II-dependent hypertension through the reduction of myocardial inflammatory cell infiltration and tyrosine hydroxylase expression." (PMID 34948475, 2021). "Numerous evidences demonstrated that salt diet elevated the noradrenaline (NE) level and tyrosine hydroxylase (TH) expression in the PVN during the process of hypertension." (PMID 34899311, 2021). "Compared with the SHAM groups, TH expression in PVN of 2K1C + scr group increased significantly, indicating that the expression of TH in the PVN is affected in the hypertension." (PMID 34938159, 2021). "TH appears to be a key component in the development of hypertension in SHR, since higher TH mRNA levels are detected in the adrenal gland and medulla oblongata of SHR than in those of WKY." (PMID 33146287, 2020). "Our results confirmed the presence of hyperactivity of the SNS in arterial hypertension, as demonstrated by increased TH and β2-AR expression in the lower brainstem and in the adrenal gland of SHR compared with WKY." (PMID 33146287, 2020). "Changes in TH activity were reported in other regions and areas of the CNS in various animal models of hypertension including the DOCA-salt model." (PMID 29495426, 2018). "Tyrosine hydroxylase (TH), the rate-limiting enzyme in catecholamines biosynthesis, is involved in hypertension development." (PMID 25710381, 2015). "Next, we examined whether hypertension alters TH-immunoreactivity—a marker of chemosensory (glomus) cells in the CB." (PMID 41160709, 2025). "Furthermore, researchers have found that resveratrol, by reducing TH expression and reactive oxygen species (ROS) levels, restores the balance of excitatory and inhibitory neurotransmitters, thereby alleviating hypertension." (PMID 39234603, 2024). "CoQ10 has also been shown to protect dopaminergic neurons against iron-induced mitochondrial dysfunction and cell death, whilst CoQ10 supplementation reduced the elevated tyrosine hydroxylase activity and NE concentration of the hypothalamic paraventricular nucleus in a hypertension model." (PMID 31412628, 2019). "It is further speculated that TH gene may be a candidate gene for the etiology of hypertension and is crucial for the pathogenesis of hypertension of human." (PMID 26229544, 2015).
Hypertension (continued). "Therefore, the expression of TH gene already elevates in the prophase of stress-induced hypertension, with a risen blood pressure as the result of overactivity of TH." (PMID 26229544, 2015). "Since TH is endogenously expressed in neurons and is increased in hypertension, we investigated whether the proteasome dysfunction observed in the hypothalamus and brainstem from SHR was also evident in neurons." (PMID 25710381, 2015). "Increased catecholaminergic neurotransmission has been reported in spontaneously hypertensive rats (SHR), characterized by increased TH activity as well as gene and protein expression, suggesting that TH plays a key role in genesis, development and/or maintenance of hypertension." (PMID 25710381, 2015). "For example, the TH gene was reported to be related to essential hypertension in Chinese subjects." (PMID 21765900, 2011). "The present study aims to understand molecular neuronal processes relevant to hypertension, involving angiotensin II (Ang II) type 1 receptor (AT1R) signaling as it regulates production of Tyrosine hydroxylase (TH)." (PMID 21167049, 2010). "In this study we investigated whether UPS regulated TH turnover in PC12 cells and hypothalamic and brainstem neurons from spontaneously hypertensive rats (SHR) and whether this system was impaired in hypertension." (PMID 25710381, 2015).
Obesity (20 papers, 2010 to 2024). Accumulation of substantial excess body fat. "The reduced density of striatal DAT with corresponding reductions in DAT and TH gene expression in substantia nigra (SN) suggests, that obesity is associated with hypodopaminergic function." (PMID 28824395, 2017). "The activation of (pro)renin receptor signaling in tyrosine hydroxylase neurons in the hypothalamic paraventricular nucleus disrupts glucose regulation and plays a pivotal role in the metabolic dysfunction associated with obesity." (PMID 38349753, 2024). "Experimental data on mice and rats confirm the DA neurotransmission deficiency and the downregulation of D2R, DA transporter (DAT), and DA synthetic enzyme tyrosine hydroxylase (TH) under conditions of a high-calorie obesity-inducing diet." (PMID 38002300, 2023). "There was a positive correlation between Peptococcaceae and the mRNA expression of dopamine receptor 1 (D1R), dopamine receptor 2 (D2R), tyrosine hydroxylase (TH), and then increased the intake of high sugar and high-fat diet during obesity." (PMID 36230124, 2022). "To further investigate how the perivascular sympathetic innervation is affected by obesity, we probed AR and TH PVAT lysates and sections for tyrosine hydroxylase." (PMID 36433953, 2022). "Consistent with our findings in mice, the tyrosine hydroxylase content was significantly lower in the epicardial fat of patients with obesity (BMI ≥ 30)." (PMID 36433953, 2022). "Beige fat expressing UCP1 provides a defence against cold and obesity, and tyrosine hydroxylase is required for the development of beige fat37." (PMID 32686763, 2020). "Compensatory changes in the DA synthesis marker TH and DA reuptake correlate with lower DA output and signaling in obesity, but it is unknown how they contribute to food intake regulation." (PMID 28824395, 2017). "For example, obesity prone rats had reductions in the DA biosynthetic enzyme tyrosine hydroxylase and vesicular monoamine transporter 2 (VMAT2) that may reduce DA synthesis and release." (PMID 28859110, 2017). "The TH mRNA downregulation is likely associated with intake of fat and independent of obesity as dopaminergic changes were observed in animals fed a high-fat diet in the absence of obesity." (PMID 24498181, 2014). "They showed that extracellular basal dopamine is low in obesity-prone rats due to reduced activity of tyrosine hydroxylase and vesicular monoamine transporter-2 and attributed susceptibility to obesity to an increased motivation to eat and increase dopamine levels." (PMID 19811894, 2010). "Notably, tyrosine hydroxylase was also decreased in the AR and TH PVAT and in the SC WAT of diet-induced obese (DIO) mice, indicating that a loss of adipose-sympathetic innervation also occurs in another model of murine obesity." (PMID 36433953, 2022). "However, whether DAT or TH gene expression is dysregulated in the condition of human obesity is still unknown." (PMID 28824395, 2017). "Further, thermoneutrality suppressed sympathetic nerve activity by inhibiting tyrosine hydroxylase expression, NE contents, and NETO, resulting in downregulation of the thermogenic program and promotion of obesity." (PMID 27230905, 2016). "Our results suggest that these functions mediated by D2 autoreceptors may be less affected in the condition of obesity than the decreases in DAT and TH gene expression." (PMID 28824395, 2017). "In both crosses, the homozygous LSL-PrRP littermates show divergent body weights at 8 to 9 weeks of age on normal chow when compared with the wild-type and the Cre-expressing mice; however, the obesity is fully reversed in the nestin-Cre::LSL-PrRP and TH-Cre::LSL-PrRP mice." (PMID 25176149, 2014). "Tyrosine hydroxylase was significantly reduced in aortas—but not hearts—from ob/ob mice, further supporting the concept that neurodegeneration is a consequence of the local alterations affecting the perivascular environment during obesity and impacting on the nearby vascular wall." (PMID 36433953, 2022).
dopa-responsive dystonia (17 papers, 2011 to 2024). "Although the disease caused by recessive genetic mutation of the tyrosine hydroxylase (TH) gene is rare, we found that the clinical manifestations of seven children with tyrosine hydroxylase gene mutations are similar to dopa-responsive dystonia." (PMID 36568392, 2022). "We present a case of mild, adult-onset dopa-responsive dystonia (DRD) with a heterozygous mutation in the tyrosine hydroxylase (TH) gene." (PMID 32018151, 2020). "A reduction in the TH protein level in the striatum has also been reported in autopsy studies of patients with Dopa-responsive dystonia (DRD), which is caused by an autosomal-dominant defect in the GCH1 gene encoding the rate-limiting enzyme for BH4 synthesis." (PMID 27798097, 2016). "Moreover, mutations in genes involved in the biosynthesis of DA encoding GTP cyclohydroxylase (DYT5), sepiapterin reductase and tyrosine hydroxylase cause dopa-responsive dystonia." (PMID 27716431, 2016). "To date, three genes have been convincingly shown to cause DOPA-responsive dystonia: GCH1 (GTP cyclohydrolase 1), TH (tyrosine hydroxylase) and SPR (sepiapterin reductase)." (PMID 23775978, 2013). "The homozygous variant found in the TH gene, c.1389C>G (p.Phe463Leu) was never before reported in children with dopa-responsive dystonia." (PMID 30894892, 2018). "Interestingly, a similar defect or delay in neuronal maturation has been described in the human disease Dopa Responsive Dystonia (DRD), characterised by dopamine deficiency as a result of a germline mutation in one of the BH4 or TH processing enzymes such as GTPCH or sepiapterin reductase." (PMID 38042898, 2023).
Alzheimer disease (15 papers, 2013 to 2025). A progressive, neurodegenerative disease characterized by loss of function and death of nerve cells in several areas of the brain leading to loss of cognitive function such as memory and language. "We suggest that altered secretagogin expression in locus coeruleus neurons is a clinicopathological sign of Alzheimer’s disease paralleling or even preceding tyrosine hydroxylase (TH) loss." (PMID 31144035, 2019). "We found reduced secretagogin expression in locus coeruleus from subjects with Alzheimer’s disease, and this reduction paralleled the loss of tyrosine hydroxylase, the enzyme rate limiting noradrenaline synthesis." (PMID 31144035, 2019). "Changes in TH expression are associated with neurodegenerative diseases such as Alzheimer’s disease, PD, and Huntington’s disease." (PMID 23902361, 2013). "Chronic neuroinflammation can decrease tyrosine hydroxylase (TH) expression in LC neurons and norepinephrine levels in projection areas such as the cortex and hippocampus, leading to cognitive impairment and Alzheimer’s disease." (PMID 35945306, 2022). "It has been reported that the reduction of TH activity is related to several neurodegenerative and neuropsychiatric diseases such as Alzheimer’s disease, Doparesponsive dystonia and PD." (PMID 30486773, 2018). "Moreover, chronic (5 weeks) peroral administration of 100 mg/kg of BH4 increased TH activity in the mouse brain and improved recognition memory in a mouse model of Alzheimer’s disease." (PMID 37892138, 2023). "However, it has been proposed that TH+ locus coeruleus neurons are most sensitive and compromised already in the early phase in Alzheimer’s disease: tau pathology appears earliest in locus coeruleus noradrenaline neurons." (PMID 31144035, 2019).
Dyskinesia (14 papers, 2012 to 2025). A movement disorder which consists of effects including diminished voluntary movements and the presence of involuntary movements. "In dyskinesia group, there was an obvious loss of TH-positive dopaminergic neuron in the 6-OHDA-lesioned ipsilateral substantia nigra." (PMID 27613848, 2016). "In mice with PD induced by MPTP, there was an increase in tyrosine hydroxylase (TH)-positive neurons, improving dyskinesia." (PMID 40001370, 2025). "The tyrosine hydroxylase inhibitor, alpha-methylparatyrosine (metyrosine), controlled the dyskinesias but induced the “off” state, indicating that the transplant-induced dyskinesias are likely dopamine-mediated." (PMID 33893319, 2021). "In PD rats that received L-dopa plus rTMS treatment for three weeks, there was a 25.3±3.4% more TH-positive dopaminergic neurons as compared with dyskinesia group (P < 0.05)." (PMID 27613848, 2016). "Although prolonged LD treatment could be responsible for the downregulation of TH, which is involved in dopamine synthesis, it may potentially lead to LD-induced dyskinesia." (PMID 40763215, 2025). "Similarly, the histological and biochemical analysis of this study also showed that low frequency rTMS-treated rats had more nigral TH-positive dopaminergic neurons and striatal dopamine level than those of the dyskinesia group and sham group." (PMID 27613848, 2016). "We suggest that the increased number of striatal TH-ir cells might be involved in the development of aberrant striatal circuits and the appearance of L-Dopa induced dyskinesias." (PMID 23226401, 2012). "When striatal dopamine production is inhibited by knockdown of the TH enzyme – causing a functional DA depletion without a structural disintegration of the synaptic terminals – pulsatile administration of exogenous L-DOPA fails to induce dyskinesia." (PMID 24614598, 2014). "Notably, the treatment of catechin extract improved the dyskinesia of crab-eating monkeys administered with MPTP, restored the levels of tyrosine hydroxylase (TH) and dopamine, decreased the level of the α-synuclein oligomer, as well as reduced their aggregation." (PMID 34204244, 2021). "If this hypothesis is true, elevated ΔFosB in sub-chronic administration of Taltirelin without dyskinesia could be explained by the increased DA stimulated by Taltirelin, and the increased DA may also help promoting TH expression in striatum." (PMID 30555300, 2018). "Our recent studies showed that Taltirelin raised TH levels in dyskinesia rats (unpublished), together with the results that AMPT blocked most DA-releasing action of Taltirelin, it is highly possible that Taltirelin could manipulate TH expression." (PMID 30555300, 2018).
behavioral disorders (13 papers, 2016 to 2024). "The S. chinensis extract improved behavioral disorders, oxidative stress-associated enzyme activities and dopamine levels and improved TH expression in the brain and protected the dopaminergic neurons." (PMID 31330885, 2019). "A reduction in tyrosine hydroxylase (TH) level in DA neurons is a major defect associated with PD and the main cause of behavioral disorders." (PMID 30838774, 2019). "Animal research has reported that acupuncture alleviates behavioral disorders in PD model rats, enhances the number of TH-positive neurons in the SN, and decreases the deposition of Fe in the SN." (PMID 38500484, 2024). "Sufficient iron levels can enhance tyrosine hydroxylase activity, thereby increasing dopamine production and alleviating mental and behavioral disorders." (PMID 39796473, 2024). "Collectively, this study investigated the potential effects of higher circulating TMAO levels on behavioral disorders, dopaminergic neurons, TH protein expression, neurotransmitter levels, and neuroinflammation in MPTP-induced PD mice." (PMID 37239262, 2023). "Damage to the striatum was confirmed by immunohistochemistry using an anti-TH antibody, and behavioral disorders in these rats were also validated by cylinder tests, stepping tests and bilateral tactile stimulation assays." (PMID 34497805, 2021). "In another study, mice injected with MPTP show an approximately 63% decrease in TH neurons and manifest typical symptoms and behavioral disorders, such as tremor, piloerection, and bradykinesia." (PMID 30524653, 2018). "Behavioral disorders occur when the number of TH-positive neurons in the SNpc of MPTP-treated mice decreases to 57.04% of the normal amount." (PMID 30524653, 2018). "The MPTP-induced vehicle mice showed behavioral disorders and significantly reduced TH expression in the midbrain tissues and DA levels, which are typical pathological features of PD." (PMID 28018211, 2016). "Different dosages of C. tubulosa nanopowder shortened the stationary duration, enhanced autonomous activities, improved behavioral disorders, elevated DA levels in the brain and increased TH expression in vehicles." (PMID 28018211, 2016). "In contrast, GM1/2/3 showed weaker effects on the behavioral disorders of PD mice than MA, but GM1/2/3 significantly inhibited the occurrence of apoptosis, increased expression of NGF and its receptors, and enhanced proteins levels of TH and DAT." (PMID 32842556, 2020).